KLHL31 (kelch like family member 31)
Description:
Transcriptional repressor in MAPK/JNK signaling pathway to regulate cellular functions. Overexpression inhibits the transcriptional activities of both the TPA-response element (TRE) and serum response element (SRE).
Synonyms: BKLHD6; KBTBD1; KLHL; bA345L23.2
Tractability: No criterion of Open Targets' tractability assessment is met for any kind of drug.
Gene: Protein-coding gene on chromosome 6 (53,647,916 to 53,665,756, reverse strand). Ensembl gene ENSG00000124743.
Gene Ontology:
Biological process: negative regulation of JNK cascade; negative regulation of protein phosphorylation; proteasome-mediated ubiquitin-dependent protein catabolic process
Cellular component: cytoplasm; nucleus; Cul3-RING ubiquitin ligase complex
Genetic constraint (gnomAD): Loss-of-function variants: 30 observed, 43.35 expected, observed/expected ratio (o/e) 0.69, 90% interval 0.52 to 0.94. The upper end of that interval is the gene's LOEUF score, 0.94, which puts it in group 3 of 6, group 1 being the genes least tolerant of losing a copy. Missense variants: 794 observed, 821.11 expected, observed/expected ratio (o/e) 0.97, 90% interval 0.91 to 1.02. Synonymous variants: 330 observed, 317.26 expected, observed/expected ratio (o/e) 1.04, 90% interval 0.95 to 1.14.
Homologues: Orthologues: chimpanzee KLHL31 (99% identical), macaque KLHL31 (99% identical), rabbit KLHL31 (96% identical), pig KLHL31 (95% identical), dog KLHL31 (93% identical), mouse Klhl31 (92% identical), rat Klhl31 (91% identical), guinea pig KLHL31 (86% identical), tropical clawed frog klhl31 (81% identical), zebrafish klhl31 (76% identical). Paralogues in human: KLHL13 (32% identical), KLHL9 (32% identical), KLHL26 (32% identical), KLHL14 (31% identical), KLHL36 (28% identical), KLHL32 (26% identical), KLHL20 (25% identical), KLHL22 (25% identical), KLHL1 (25% identical), KLHL17 (25% identical), KLHL28 (24% identical), KLHL18 (24% identical), and 42 more.
Diseases named in the same sentence as KLHL31 in open-access papers:
KLHL31 is named in the same sentence as 28 diseases in open-access papers, as found by Europe PMC text mining. Sharing a sentence is not in itself a finding about the gene and the disease. The quoted sentences say what the papers report.
centronuclear myopathy (1 paper, 2023). Centronuclear myopathy (CNM) is an inherited neuromuscular disorder characterized by clinical features of a congenital myopathy and centrally placed nuclei on muscle biopsy. "Similarly, mice lacking Klhl31 exhibit stunted skeletal muscle growth, centronuclear myopathy, and SR dilation." (PMID 38092777, 2023).
Takayasu arteritis (1 paper, 2023). A rare inflammatory large-vessel vasculitis primarily affecting the aorta and its major branches, but also other large vessels, causing stenosis, occlusion, or aneurysm. "KLHL31, which is abundant in human and mouse cardiomyocytes, was downregulated in human HCM and KLHL33 has been reported as relevant locus in Takayasu’s arteritis in humans." (PMID 36928240, 2023).
KLHL31 also shares sentences with these, for which no sentence is quoted: cancer (8 papers); tumor (4); Chronic Lymphocytic Leukemia (2); nemaline myopathy (2); Alzheimer disease (1); asthma (1); autoimmune encephalitis (1); Autoimmunity (1); brain tumors (1); brainstem atrophy (1); cardiovascular disorder (1); Cerebellar atrophy (1); chromophobe renal cell carcinoma (1); colorectal carcinoma (1); gastric cancer (1); genetic diseases (1); Glycogen Storage Disease (1); leiomyosarcoma (1); Liver Carcinoma (1); lung adenocarcinoma (1); osteoarthritis (1); prostate adenocarcinoma (1); renal carcinoma (1); schwannoma (1); testicular seminoma (1); tumor of ovary (1).